ADA (adenosine deaminase)
Diseases named in the same sentence as ADA in open-access papers (continued):
Sharing a sentence is not in itself a finding about the gene and the disease.
cancer (99 papers, 1978 to 2026). A tumor composed of atypical neoplastic, often pleomorphic cells that invade other tissues. "The cancer ratio plus (CR+), a potential diagnostic tool calculated as serum lactate dehydrogenase/(pleural adenosine deaminase x pleural lymphocyte percentage) has emerged to address this diagnostic challenge." (PMID 41399654, 2026). "ADA1 and ADA2 are two adenosine deaminases in humans, and changes in ADA activity are associated with pathological conditions, such as immune disorders and cancer." (PMID 40936927, 2025). "It is reported that for some cancers, a decrease in the activity of ADA is associated with a progression of such diseases as head and neck, prostate, and laryngeal squamous cancer." (PMID 35327609, 2022). "This underlines the impact of factors secreted by cancer cells on the increase of the cell-surface ADA activity in endothelial cells." (PMID 33916440, 2021). "Here, through analysis of genome-scale loss-of-function datasets, we identify adenosine deaminase acting on RNA (ADAR or ADAR1) as an essential gene for the survival of a subset of cancer cell lines." (PMID 30575730, 2018). "High ADA activity might be advantageous to the cancer cells by causing, in association with purine nucleoside phosphorylase (PNP), an increase in hypoxanthine, a substrate for the salvage pathway." (PMID 31547393, 2019). "Tudor-SN is a member of the RISC complex and also known as SND1, and it has been implicated in various cancers and has been shown to regulate miRNA processing and expression by degrading primary-miRNA transcripts that undergo adenosine deaminase acting on RNA (ADAR) editing." (PMID 26097876, 2015). "ADA, a housekeeping enzyme crucial in purine metabolism, makes a certain contribution to the regulation of inflammatory reactions and immune status, and its inhibitor has been shown to be obviously associated with reduced tumor size and decreased aggressiveness of cancer cells." (PMID 36212161, 2022). "In several studies, the CR+ outperformed both ADA alone and the original Cancer Ratio (serum LD/pleural ADA)." (PMID 41399654, 2026). "Our results uncover an oncogenic role of ADAT2/3 and identify this adenosine deaminase as a possible new pharmacologically tractable target for cancer therapy." (PMID 40907939, 2025). "Low purine levels can slow cell proliferation, whereas high levels of purines are often seen in rapidly dividing cells, such as cancer cells, and high ADA activity occurs in various diseases and disorders including different cancers." (PMID 41360777, 2025). "It has been reported that treatment with LDC067 induced apoptosis in several cancer cell lines, which was assumed to be due to loss of short-lived apoptotic transcripts while we firstly found that LDC067 decreased ADA expression in vitro and in vivo." (PMID 41360777, 2025). "The rs174537 genotype significantly influenced both omega-3 and omega-6 LC-PUFAs in tumor tissue, the G allele being associated with higher AA, ADA, DPA, and DHA levels and lower LA and DGLA levels—promoting cancer cell growth." (PMID 40430008, 2025). "The enzymes involved in purine metabolism are overexpressed in various cancer, such as adenosine deaminase (ADA), cytoplasmic-5’-nucleotidase-II (CN-II) and inosine monophosphate dehydrogenase (IMPDH1)." (PMID 39343971, 2024). "Conversely, in MPE, low ADA levels are observed due to suppressed immune function in cancer patients, resulting in reduced ADA activity in lymphocytes." (PMID 38750432, 2024). "Adenosine is rapidly taken back into cells and converted to inosine by ADA, which has also been shown to have immunosuppressive consequences in cancer models." (PMID 37187740, 2023). "Cancer ratio (CR), which is defined as serum lactate dehydrogenase (LDH) to pleural fluid adenosine deaminase (ADA) ratio, has been reported to be a useful diagnostic marker for malignant pleural effusion (MPE)." (PMID 37286973, 2023).
cancer (continued). "The adenosine deaminase acting on RNA (ADAR) enzymes was associated with the highly aggressive biologic behaviour and poor prognosis in many cancers." (PMID 37189448, 2023). "In cancer patients, alterations in adenosine deaminase (ADA) activity can lead to increased levels of adenosine as ADA normally deactivates adenosine by converting it to inosine." (PMID 37601668, 2023). "Combination treatment with cordycepin (1–20 μM) and 1 μM of pentostatin also induced significantly decreased cell growth in cancer cell lines with both high and low ADA levels." (PMID 35804893, 2022). "Changes in the activity of ADA are detected in patients with various cancer types, suggesting a role in carcinogenesis." (PMID 36407311, 2022). "Very recently, it has been shown that a new analog of cordycepin, NUC-7738, which is resistant to ADA, has anti-cancer activities in cancer cells, providing additional evidence for the importance of ADA in modulating the effects of this adenosine analog." (PMID 35804893, 2022). "An intensification of ADA activity is observed in patients with different diseases, including cancer." (PMID 35327609, 2022). "A decreased activity of ADA in the peripheral lymphocytes is observed in patients with stage IV cancer." (PMID 35327609, 2022). "In the 4T1 model, tumor growth and metastasis formation were decreased by the inhibition of CD73 or of adenosine deaminase, indicating that it is a deregulation of eAdo levels that can inhibit cancer progression." (PMID 35628582, 2022). "A recent study showed that PEGylated ADA2 injection inhibited the growth of several solid tumors (including colon and breast tumors) and lung metastasis in tumor-bearing mice models, which indicated the potential value of ADA in cancer therapy." (PMID 35663977, 2022). "We also examined the potential relationship between ADA activity and cancer progression in TNBC patients." (PMID 33916440, 2021). "Then, we analyzed the effects of interactions between immune, endothelial, and cancer cells on ADA iso-enzyme activities in MDA-MB-231 cells." (PMID 33916440, 2021). "This experimental setup allowed to check the effects of cancer cell-released factors on ecto-ADA iso-enzyme pattern in immune and endothelial cells." (PMID 33916440, 2021). "ADA is an enzyme involved in purine metabolism and is elevated in plasma from patients with inflammatory diseases and cancer." (PMID 34206510, 2021). "ADA activity has also been characterized in leukemic cells, normal epidermal and carcinoma cells, mouse intestines, human and chicken livers, mollusk (Biomphalaria glabrata) hemolymph, and zebrafish brain." (PMID 34037096, 2021). "Pre and post-treatment with C. ignea suppressed the elevation of ADA activity in B(a)P-treated mice, which consequently decreased the proliferation rate of cancer cells in both groups, thereby highlighting the antiproliferative effect of C. ignea extract." (PMID 31660294, 2019). "The elevated ADA activity observed in B(a)P-treated mice reveals an accelerated salvage pathway, which provides more nucleotides to highly proliferating cancer cells." (PMID 31660294, 2019). "Conflicting information on the relationship between ADA and cancer has been reported in previous studies, some of which have found ADA activity to be increased in malignant tissues and others of which have found it to be decreased." (PMID 29854023, 2018). "The extent of ADA inhibition is related to adenosine metabolism by cancer cells and is different for various solid tumor targets." (PMID 30514403, 2018). "Specific, affinity-purified IgYs were able to recognize human recombinant ADA and ADA present in human cancer cell lines." (PMID 29043661, 2018). "Although ADA has been suggested as a potential marker for several types of cancer, the importance of each of ADA isoforms as well as their levels and enzymatic activities in tumors need to be further investigated." (PMID 29043661, 2018).
cancer (continued). "Although statins suppress OPN in cancer cells, little is known about their effects on ADA and OPN in COPD patients." (PMID 27557561, 2016). "Previous studies have indicated that disturbed adenosine deaminase acting on RNA (ADAR) expression is able to alter mRNA and miRNA adenosine to inosine (A-to-I) levels associated with cancer pathogenesis." (PMID 25673044, 2015). "Therapeutic targeting of the adenosine deaminase ADAR has great potential in cancer and other indications; however, it remains unclear what approach can enable effective and selective therapeutic inhibition." (PMID 39992915, 2025). "In most cancer types, adenosine deaminase is positively correlated with infiltrating immune cells, and its elevated expression may serve as an indicator of poor survival rates." (PMID 39546272, 2025). "Studies have found that ADA levels in ascites of cancer patients are significantly reduced." (PMID 39737405, 2024). "This suggests that high ADA levels may decrease atezolizumab exposure, potentially reducing its anti-cancer efficacy." (PMID 39445019, 2024). "However, the specific roles of ADA and 6-hydroxy-2-aminohexanoic acid in cancer are currently limited." (PMID 38610016, 2024). "The activity of ADA is reported to be upregulated in patients with cancer." (PMID 39445019, 2024). "Previously, we have reported that adenosine-converting ecto-enzyme, which is a cell surface adenosine deaminase (ADA), may serve as a biomarker of endothelial activation and vascular inflammation in cardiovascular pathologies, neurodegeneration, and cancer." (PMID 37685949, 2023). "Overexpression of adenosine deaminase has been reported in the progress of various diseases, including cancers, which is why inhibition of the enzyme may be a possible treatment strategy." (PMID 35684435, 2022). "Finally, six indicators of age, sex, cancer, CRP, T-SPOT, and ADA were included in the diagnostic scoring model by multivariate binary logistics regression, which showed that those six indicators significantly contributed significantly to the diagnosis." (PMID 36056429, 2022). "The changes in the activity of ADA are detected in patients with various cancer types." (PMID 35327609, 2022). "Both genetic and small molecule ADA inhibition sensitized cancer cells to cordycepin." (PMID 35804893, 2022). "We hypothesized that ectopic expression of ADA in cancer cells could result in cytosolic retention and low secretion." (PMID 34948316, 2021). "We compared the diagnostic potential of cancer ratio (CR, serum lactate dehydrogenase [LDH]/pleural fluid adenosine deaminase [pfADA]), cancer ratio plus (CR plus, cancer ratio/pleural lymphocyte percentage), and age/pfADA ratio with pfADA in malignant pleural effusion." (PMID 33909825, 2021). "Low ADA activity in lymphocytes, as outlined later on in this section, could account for the decreased cellular immune function in cancer patients." (PMID 31547393, 2019). "It is important to highlight that different isozymes/molecular forms of ADA have been found in tumor cells, which may indicate that the composition of isoforms during cancer progression may change." (PMID 29043661, 2018). "The anti-cADA IgY antibodies were able to specifically recognize ADA in human cancer cell lysates." (PMID 29043661, 2018). "Aberrant adenosine-to-inosine (A-to-I) RNA editing, catalyzed by adenosine deaminase acting on double-stranded RNA (ADAR), has been implicated in various cancers, but the mechanisms by which microRNA (miRNA) editing contributes to cancer development are largely unknown." (PMID 36599932, 2023). "This review aims to present the role of purinergic signaling highlighting the ectonucleotidases E-NTPDase, E-NPP, E-5′-nucleotidase, and adenosine deaminase in noncommunicable, neurological, and degenerative diseases associated with the cardiovascular and central nervous systems and cancer." (PMID 30159340, 2018).
cancer (continued). "Body fluid adenosine deaminase (ADA) levels have a sensitivity and specificity of 93% and 96%, but they can have false negatives in malignant ascites and HIV." (PMID 40978883, 2025). "For example, dysregulation of enzymes involved in this pathway, such as adenosine deaminase (ADA) and purine nucleoside phosphorylase (PNP), has been shown to promote tumor growth and metastasis in certain types of cancer." (PMID 39330508, 2024). "Still, there were significant differences among age, male, cancer diagnosis, pleural fluid location, fever, ESR, CRP, T-SPOT, pleural fluid lymphocyte ratio, and ADA (p < 0.05)." (PMID 36056429, 2022). "Targeting enzymes in the TME that decrease the levels of adenosine (such as ADA and ADK) can significantly prevent the activation of adenosine receptors and enhance cancer immunotherapy." (PMID 35327609, 2022). "RALGPS1, NUDT9, NUDT2, and PDE4A were less expressed in cancer cell lines; JUP, ADA, HPRT1, and IMPDH1 were highly expressed in cancer cell lines in CCLE." (PMID 34745385, 2021). "In the hypoxic niche of cancer, Tregs, MDSCs, CAFs, and cancer cells themselves upregulate CD39/CD73 and downregulate ADA to favor eADO accumulation and immune suppression." (PMID 34948316, 2021). "In parallel, it has been observed a down-regulation of the catabolic enzyme ADA and its cofactor CD26 (also known as dipeptidyl peptidase 4) as well as the reduction of adenosine kinase activity in the cancer microenvironment." (PMID 32708507, 2020). "ADA, along with a few other enzymes (for example HGPRT), are responsible for purine metabolism and are well known targets for cancer chemotherapy." (PMID 31351478, 2019). "While our studies on the antitumour potential of ADA activity inhibition have been performed in mice that lack ADA2, which plays a key role in the abolishment of immune surveillance leading to cancer progression, dCF is known to affects both ADA isoenzymes." (PMID 30291675, 2018). "However, the studies about ADA in cancers are still few, and the roles of ADA1 and ADA2 in pan-cancer are still unclear." (PMID 35663977, 2022). "Noteworthy, the activity of ADA (ADA1 and ADA2) changes during the interaction of tumor cells (triple-negative breast cancer) with lymphocytes, macrophages, and endothelial cells in vitro, providing unfavorable phenotype and contributing to cancer progression." (PMID 35327609, 2022). "The maximum change in the activities of AHH, γ-GT, 5′-NT, ADA, and LDH to the normal level in the serum by a high dose of DATSL, in combination with DOXL, clearly indicated the former’s role in the delay in cancer initiation, while later inhibited its promotion." (PMID 35408590, 2022). "Unlike TPE, the immune function of patients with cancer is suppressed, resulting in a decrease in the activity of ADA in lymphocytes." (PMID 33909825, 2021). "Interestingly, at lower MOIs (0.1 and 1 pfu/cell), THV_ADA and THV_ADA-SP resulted in being even more cytotoxic than the unarmed R-LM113, presumably due to the deprivation of eADO, known to sustain cancer cell viability." (PMID 34948316, 2021). "4T1 cell orthotopic implantation did not affect total ADA and eADA activities measured 28 days after cancer cell injection, while dCF treatment decreased both activities by about 70%." (PMID 30291675, 2018). "dCF inhibited ADA activity by about 50% as compared to its activity after 2 days of cancer cell injection, without affecting its activity compared to control values." (PMID 30291675, 2018). "At the cut-off level of >20, the PLR value was 32.6 suggesting that patients with cancer have about 32 fold higher chance of having cancer ratio (Serum LDH: Pleural fluid ADA ratio) of >20 compared with patients without cancer." (PMID 26678281, 2016). "However, the function and clinical value of ADA in cancers have not been well analyzed, including ADA1 and ADA2." (PMID 35663977, 2022).
cancer (continued). "Despite the fact that SP did not improve ADA secretion in our cell model, we speculate that it might be useful in different cancer cells less able to secrete ADA." (PMID 34948316, 2021). "Consistently, data from our earlier human phase I trails for TRAIL-Trimer18 with multiple intra cavity infusions with dosage up to 120 mg which is over 1000X that to be used for S-Trimer subunit vaccine has shown no ADA induced (anti drug antibody) in the cancer patients." (PMID 33649323, 2021). "Moreover, arming with ADA, not only is not detrimental for viral replication, but also improved cancer cell cytotoxicity, presumably through an eADO-deprivation-mechanism." (PMID 34948316, 2021). "The analysis of TNBC patients, at 6 and 12 months following cancer treatment, did not showed significant changes in plasma ADA activities and macrophage polarization markers, which may be the cause of their therapeutic failure." (PMID 33916440, 2021). "Interestingly, in inflamed areas of cancer tissue, it has been observed an increase CD39 and CD73 expression and activity along with a reduction in ADA and CD26 expression, resulting in a marked and persistent increase in extracellular adenosine concentrations." (PMID 32708507, 2020). "In contrast, we observed that cordycepin significantly suppressed EBV gene expression and lytic reactivation; and secondly, adenosine deaminase (ADA) converts cordycepin to 3′-deoxyinosine which does not exhibit anti-cancer effects as much as the original cordycepin." (PMID 30875759, 2019). "Our study suggests several possible approaches to disrupt the function of ADAR1 in cancer cells: direct enzymatic inhibition of its adenosine deaminase activity and/or inactivation of non-enzymatic functions unique to the p150 isoform, such as direct PKR binding." (PMID 30575730, 2018). "The efficient intracellular elimination of this product by adenosine-transforming enzymes, such as adenosine deaminase (ADA), or its transport out of the cells by specific adenosine transporters, such as the equilibrate nucleoside transporters (ENTs), is of vital importance for cancer cell survival." (PMID 23251702, 2012). "Cancer cells could be a potential source of ADA, but this has not been comprehensively studied." (PMID 30291675, 2018). "The results showed that ADA, ATP1B3, DYNC1H1 and FTCD were differently expressed in non-cancer vs. cancer tissues of different stages, in cancer tissues of stage I vs. stage II or stage I vs. stage III." (PMID 35739471, 2022). "It was shown that in patients with cancer, the levels of adenosine in tumor cells are regulated primarily by ADK-mediated phosphorylation to AMP and not the effect of ADA." (PMID 35327609, 2022). "Six variables were selected in the scoring model: Age ≤ 46 years old (4.96 points), Male (2.44 points), No cancer (3.19 points), Positive T-cell Spot (T-SPOT) results (4.69 points), Adenosine Deaminase (ADA) ≥ 24.5U/L (2.48 point), C-reactive Protein (CRP) ≥ 52.8 mg/L (1.84 points)." (PMID 36056429, 2022). "Therefore, some ADA inhibitors (such as erythro-9-(2-hydroxy-3-nonyl)adenine, EHNA) induce apoptosis of malignant tumor cell lines and suppress tumor growth by increasing intracellular adenosine/deoxyadenosine concentration." (PMID 29043661, 2018).